DGUOK (deoxyguanosine kinase)
Diseases named in the same sentence as DGUOK in open-access papers (continued):
Sharing a sentence is not in itself a finding about the gene and the disease.
lung adenocarcinoma (3 papers, 2020 to 2023). A carcinoma that arises from the lung and is characterized by the presence of malignant glandular epithelial cells. "We have previously shown frequent overexpression of DGUOK in lung adenocarcinoma and close association of elevated expression of DGUOK with tumor progression and patient survival." (PMID 33392072, 2020). "Furthermore, we have shown frequent overexpression of DGUOK-NMNAT2 in lung adenocarcinoma and the association of this pathway with poor prognosis of this malignancy." (PMID 33392072, 2020). "DGUOK was frequently overexpressed in lung adenocarcinoma and aberrant expression of DGUOK correlated with tumor progression and patient overall survival." (PMID 35358513, 2022). "Overexpression of DGUOK promotes mitochondria oxidative phosphorylation and lung adenocarcinoma progression." (PMID 33392072, 2020). "Similar to the DGUOK, high levels of NMNAT2 were associated with the poor overall survival of patients with lung adenocarcinoma." (PMID 33392072, 2020). "We have previously shown that DGUOK was frequently overexpressed in lung adenocarcinoma and aberrant expression of DGUOK correlated with tumor progression and patient overall survival." (PMID 33392072, 2020). "We have recently reported frequent overexpression of DGUOK lung adenocarcinoma." (PMID 33392072, 2020). "We have recently reported that DGUOK overexpression promotes lung adenocarcinoma progression." (PMID 33392072, 2020). "Collectively, these results indicated that DGUOK-NMNAT2 axis is frequently elevated in lung adenocarcinoma and could be served as poor prognostic biomarker in this malignancy." (PMID 33392072, 2020). "Furthermore, we recently reported DGUOK promote cancer cell stemness in lung adenocarcinoma." (PMID 33392072, 2020). "In this study, we found that NMNAT2 mediates NAD+ biogenesis induced by DGUOK and that the NMNAT2 expression negatively correlates with overall survival in the patients with lung adenocarcinoma." (PMID 33392072, 2020). "As DGUOK-NMNAT2 induces NAD+ biogenesis, the DGUOK-NMNAT2-NAD+ pathway could be potential therapeutic target in lung adenocarcinoma." (PMID 33392072, 2020). "We found that the DGUOK and the NMNAT2 were dramatically up-regulated in lung adenocarcinoma." (PMID 33392072, 2020). "Our study suggested that DGUOK regulates NAD+ in a NMNAT2 dependent manner and DGUOK-NMNAT2-NAD+ axis could be a potential therapeutic target in lung adenocarcinoma." (PMID 33392072, 2020). "Collectively, our data indicate that the DGUOK-NMNAT2-NAD+ axis could be a prognostic marker and a critical therapeutic target in lung adenocarcinoma." (PMID 33392072, 2020).
cholestasis (2 papers, 2021 to 2024). Impairment of the bile flow caused by obstruction within the liver, or outside the liver in the bile duct system. "The hepato-cerebral forms, combining early hepatic damage (cytolysis, hepatocellular failure, cholestasis) and axial hypotonia, are due to mutations in the DGUOK genes encoding deoxyguanosine kinase, POLG encoding gamma mitochondrial DNA polymerase or MPV17 of unknown function." (PMID 34680481, 2021).
hyperinsulinemic hypoglycemia (2 papers, 2023). An inherited autosomal recessive syndrome characterized by the disorganized formation of new islets in the pancreas and congenital hyperinsulinism. "Our two cases now support a pattern of hyperinsulinemic hypoglycemia in DGUOK deficiency, thus warranting consideration of this mitochondrial disease in the workup of HI." (PMID 38027095, 2023).
citrin deficiency (1 paper, 2021). "Two patients had inherited metabolic disorders: citrin deficiency (n = 1) and deoxyguanosine kinase deficiency (n = 1)." (PMID 34440401, 2021).
developmental delay (1 paper, 2025). "Patients with infantile-onset DGUOK deficiency also develop neurological diseases, including hypotonia, developmental delay, ptosis, rotatory nystagmus, and seizures." (PMID 39897640, 2025).
Encephalopathy (1 paper, 2021). Encephalopathy is a term that means brain disease, damage, or malfunction. "Mutations in POLG and DGUOK have been previously implicated in mitochondrial disorders with common phenotype such as mitochondrial respiratory complex defect, mitochondrial DNA depletion and encephalopathy." (PMID 33484326, 2021).
female infertility (1 paper, 2024). Diminished or absent ability of a female to achieve conception. "Our findings reveal novel physiological roles for the mitochondrial nucleoside salvage pathway in oocyte maturation and implicate DGUOK as a potential marker for the diagnosis of female infertility." (PMID 38327186, 2024).
hypermethioninemia (1 paper, 2016). "Some reports have linked hypermethioninemia and hepatic abnormality to mitochondrial depletion syndrome caused by mutations in the MPV17 and DGUOK genes." (PMID 27500280, 2016).
Hypothermia (1 paper, 2020). Reduced body temperature due to failed thermoregulation. "Hypothermia was also observed in one patient with DGUOK deficiency." (PMID 32703289, 2020).
Infertility (1 paper, 2024). "Moreover, DGUOK-mediated mitochondrial dysfunction plays important roles in oocyte maturation and infertility." (PMID 38327186, 2024).
ovarian insufficiency (1 paper, 2024). "In addition, the ovarian insufficiency caused by DGUOK deficiency also provides a potential molecular target for the pathogenesis of primary ovarian insufficiency (POI)." (PMID 38327186, 2024).
pneumothorax (1 paper, 2023). Abnormal presence of air in the pleural cavity. "A 12-year-old Russian boy with deoxyguanosine kinase deficiency, a recipient of a liver transplant with amyotrophy secondary to his mitochondriopathy, presented with recurrent spontaneous bilateral pneumothorax refractory to drainage and surgery." (PMID 37775787, 2023). "Increased production of ROS in the lung region may contribute to spontaneous pneumothorax in DGUOK deficiency, as well as amyotrophy itself." (PMID 37775787, 2023). "The pneumothorax presented by our patient could be considered as a late consequence of DGUOK deficiency." (PMID 37775787, 2023). "So far, to the best of our knowledge, there is no existing data describing the association between DGUOK deficiency and recurrent spontaneous pneumothorax." (PMID 37775787, 2023). "The association between deoxyguanosine kinase deficiency and recurrent spontaneous pneumothorax has not currently been reported." (PMID 37775787, 2023). "We present the case of a 12-year-old child with DGUOK deficiency having recurrent spontaneous pneumothorax, which, to date, has never been described in the literature as associated with DGUOK deficiency." (PMID 37775787, 2023).
systemic lupus erythematosus (1 paper, 2020). An autoimmune multi-organ disease typically associated with vasculopathy and autoantibody production. "In addition, SNPs mapped to DGUOK were associated with systemic lupus erythematosus at PGWAS < 5E-08." (PMID 32429084, 2020).
mitochondrial disease (6 papers, 2016 to 2023). "Also, patients with mitochondrial diseases affecting muscle argue against this (TK2, SUCLA2, SUCLG1, RRM2B, DGUOK, and TYMP)." (PMID 30538797, 2018).
tumor (3 papers, 2019 to 2022). "Our results indicate that DGUOK plays a pivotal role in mitochondrial function and tumor progression through regulation of the NMNAT2." (PMID 33392072, 2020). "IHC staining of harvested tumor tissues from the LLC model further confirmed the reduction of YAP1 levels from DGUOK depletion." (PMID 31633874, 2019). "Depletion of DGUOK in lung adenocarcinoma cells markedly inhibited tumor growth and lung colonization in xenograft and allograft mouse models." (PMID 31633874, 2019). "Taken together, our data indicate that DGUOK overexpression in lung adenocarcinoma is essential for both tumor growth and metastasis." (PMID 31633874, 2019). "And EV2G, the depletion of DGUOK dramatically inhibited tumor sphere formation in LLC, H1650, A549, and three PDCs." (PMID 31633874, 2019). "The depletion of DGUOK robustly inhibited lung adenocarcinoma tumor growth, metastasis, and CSC self‐renewal." (PMID 31633874, 2019). "Our data suggest that genetic targeting of DGUOK induced tumor regression through inhibition of mitochondrial OXPHOS and YAP1 signaling." (PMID 31633874, 2019). "Genetic targeting of DGUOK using doxycycline‐inducible CRISPR/Cas9 was able to markedly induce tumor regression." (PMID 31633874, 2019). "The depletion of DGUOK inhibited the growth of orthotopic primary tumor (left lung) by 75% and the development of local metastases (right lung) by 91%." (PMID 31633874, 2019). "Doxycycline‐induced DGUOK depletion inhibited 90% of tumor initiation." (PMID 31633874, 2019). "To further determine the role of DGUOK in lung adenocarcinoma progression, we used immunohistochemistry (IHC) to evaluate DGUOK expression levels in 82 pairs of lung adenocarcinoma specimens and para‐tumor lung tissues." (PMID 31633874, 2019). "Similarly, ectopic expression of DGUOK in DGUOK KO LLC cells was able to partially restore tumor initiation at 1 × 105 dilution (7 out of 8)." (PMID 31633874, 2019). "To determine whether DGUOK targeting could prevent tumor initiation, we used a Tet‐On CRISPR/Cas9 system, where doxycycline treatment could efficiently induce the expression of Cas9 and the depletion of DGUOK protein levels in approximately 1 week." (PMID 31633874, 2019). "Consistent with the tumor initiation experiment, ectopic NDI1 and DGUOK were able to restore tumor growth in DGUOK KO LLC cells (and EV5D and E)." (PMID 31633874, 2019). "Intriguingly, the tumors from the NDI1 OE groups (1 × 105 dilution, in either control or DGUOK KO LLC cells) were moderately larger than the control group, implicating a role of mitochondrial OXPHOS in tumor growth." (PMID 31633874, 2019). "To further critically evaluate the role of DGUOK and mitochondrial OXPHOS in CSC self‐renewal, we used a limiting dilution tumor initiation assay to determine the effects of DGUOK depletion, DGUOK rescue, and NDI1 rescue on cancer cell stemness." (PMID 31633874, 2019). "The expression levels of DGUOK were robustly correlated with tumor size, nodal involvement, and TNM staging but not with the age, gender, or smoking status of patients (Table EV1)." (PMID 31633874, 2019). "The ectopic expression of NDI1 in DGUOK KO LLC cells was able to rescue tumor formation at the 1 × 105 cell dilution (8 out of 8), but not at higher dilutions (1 × 104 or 1 × 103) suggesting at least partial rescue of cancer cell stemness in DGUOK KO cells by restoration of mitochondrial OXPHOS." (PMID 31633874, 2019).
cancer (2 papers, 2020 to 2021). A tumor composed of atypical neoplastic, often pleomorphic cells that invade other tissues. "It has been shown that DGUOK promotes the lung adenocarcinoma cancer progression and cancer stemness through mitochondria complex I activity." (PMID 33392072, 2020).
heart disease (1 paper, 2020). "For example, while CDK13, CHD4, KDM5A, and SCN10A are related to familial heart disease, CFH, DGUOK, and POLE are related to familial vascular disease." (PMID 31941532, 2020).
neurodevelopmental disorder (1 paper, 2022). A behavioral and cognitive disorder with onset during the developmental period that involves impaired or aberrant development of intellectual, motor, or social functions. "DGUOK does not have an obvious immune system role and has been primarily studied in the context of mitochondrial DNA depletion and neurodevelopmental disorders." (PMID 35741778, 2022).
DGUOK also shares sentences with these, for which no sentence is quoted: epilepsy (3 papers); metabolic disorders (3); mitochondrial DNA depletion syndrome 3 (3); myopathy (3); Mitochondrial myopathy (2); acute liver failure (1); Ataxia (1); autoimmune hemolytic anemia (1); cardiomyopathy (1); Cerebral atrophy (1); cystic fibrosis (1); diabetes (1); Epileptic encephalopathy (1); Failure to thrive (1); galactosemia (1); Gaucher disease (1); giant-cell hepatitis (1); glycogen storage diseases (1); GRACILE syndrome (1); hearing loss (1); Hyperinsulinemia (1); hypertrophic cardiomyopathy (1); Infantile onset (1); infection (1); iron overload (1); lactic acidosis (1); leukemia (1); lysosomal storage disorders (1); MELAS (1); Mitochondrial encephalopathy (1).
A further 10 diseases each share a sentence with DGUOK in 1 paper.